CDH1 (cadherin 1)
Diseases named in the same sentence as CDH1 in open-access papers (continued):
Sharing a sentence is not in itself a finding about the gene and the disease.
cancer (continued). "E-cadherin, an important protein encoded by CDH1 gene to mediate cell adhersion, has been reported to be commonly mutated in diffuse-type gastric cancer to contribute to cancer dissemination." (PMID 27058427, 2016). "Because of the link between E‐cadherin and cancer, CDH1 mutations are assessed in various cancer risk gene panels." (PMID 27064202, 2016). "Previous studies denote that CDH1 is a negative regulator of the translocation of β-catenin from the cell membrane to the cytoplasm and nucleus, which has been implicated in cancer development and progression." (PMID 27801803, 2016). "Five nonsynonymous germline variants on 4 cancer susceptible genes, CDH1, APC, MLH1, and NRAS, were observed in 6 patients with CRC (12%)." (PMID 27121310, 2016). "Clearly, further characterization of the phenotype and cancer risks of CDH1 mutation carriers will be needed in order to guide screening and surgical interventions appropriately." (PMID 27064202, 2016). "Although some cancer cell lines were reported to have loss of Cdh1 expression, analysis of TCGA data shows that APC/C components and Cdh1 are not commonly inactivated in human cancers." (PMID 26650195, 2016). "Well-designed, unbiased, and large case-control studies should be performed to acquire a more precise association between the CDH1 -160C/A polymorphism and cancer risk." (PMID 27349965, 2016). "CDH1 promoter methylation had an increased risk in cancer tissues (OR = 8.71, 95 % CI = 4.87 - 15.58, P < 0.001) in comparison with nonmalignant tissues." (PMID 27067410, 2016). "SNAIL, ZEB, and basic helix-loop-helix (bHLH) factors ally to mediate the dynamic silencing of CDH1, and loss of CDH1 function is a hallmark of carcinoma cell invasiveness." (PMID 27496222, 2016). "A hallmark of cancer metastasis is the loss of CDH1 expression, and hypermethylation within the CDH1 promoter region is also observed in GC." (PMID 25874772, 2015). "CDH1 (hypermethylated) encodes E-Cadherin, a known surface adhesion molecule downregulated in cancers." (PMID 26683690, 2015). "CDH1 mutations are known to be prevalent in several types of cancers: gastric, colorectal, breast, thyroid, and ovarian." (PMID 24690483, 2014). "They demonstrated that miR-9 directly targets CDH1, the E-cadherin- encoding mRNA, leading to down-regulation of E-cadherin and increase in cancer cell motility and invasiveness." (PMID 25552204, 2014). "In this study, we assessed if polymorphic variants in the cancer predisposing gene CDH1 are associated with NSCL/P in a sample from the Polish population." (PMID 24838934, 2014). "Both the primary and the metastasis contained cancer driver events that were likely to be critical for tumorigenesis in the context of the initial CDH1 mutation." (PMID 25315765, 2014). "We found a strong association between the cancer predisposing gene CDH1 and the risk of NSCL/P in the Polish population." (PMID 24838934, 2014). "Inactivation of CDH1 is associated with its dysfunction in cell-cell adhesion as well as triggering of cancer invasion and metastasis." (PMID 24165089, 2013). "There are several mechanisms for abnormal ECAD expression in cancer, including allelic loss at the CDH1 locus as well as somatic and, rarely, germ line mutations." (PMID 21639893, 2011). "Decreased CDH1 expression is observed in many cancers, a significant correlation between loss of CDH1 expression and invasion and metastasis has been documented." (PMID 22547956, 2011). "The infiltrating and scattered type of growth in diffuse-type GC has been reported to be mediated by loss of E-cadherin (CDH1) function through somatic mutation, promoter methylation, and cancer-associated downregulation." (PMID 19107131, 2009). "Testing for mutations in the CDH1 gene may be recommended for individuals with a personal or family history of these types of cancer." (PMID 39996890, 2025).
cancer (continued). "Thus, the identification of CDH1 mutations not only aids in cancer risk stratification but also informs clinical decision-making regarding surveillance and preventive strategies." (PMID 40585607, 2025). "Research indicates that individuals with CDH1 mutations may benefit from proactive surveillance strategies, including endoscopic screening and prophylactic surgeries, to mitigate cancer risk." (PMID 40585607, 2025). "These dietary habits may exacerbate the effects of H. pylori infection and the presence of CDH1 mutations, potentially leading to increased oxidative stress and inflammation in the gastric mucosa, which are known contributors to cancer development." (PMID 40585607, 2025). "In addition, understanding why CDH1 mutations drive tumorigenesis in both gastric and breast tissue is essential for clarifying the variable cancer risks among carriers." (PMID 40366456, 2025). "Dysregulation of CDH1 is often associated with cancer progression and metastasis." (PMID 40919176, 2025). "CDH1 (E-cadherin) loss is the hallmark genetic alteration in human diffuse-type gastric cancer, and this model provides insight into the earliest events in this aggressive cancer subtype." (PMID 40673273, 2025). "These promising results indicate that the AI-based model can robustly classify ILCs and uncover CDH1 inactivating mechanisms, paving the way for the development of diagnostic AI models applied to pathology that facilitate accurate cancer diagnosis and biologic discoveries." (PMID 39941785, 2025). "CDH1, a transmembrane protein, is closely associated with cancer cell proliferation and metastasis." (PMID 38698370, 2024). "Suppression of cdh1 expression by promoter methylation has been demonstrated in various cancers including prostate and breast, and was reported to be associated with higher-grade cancers." (PMID 38396852, 2024). "It has been reported that mutations in CDH1 are associated with GC, and its loss of function may contribute to cancer progression by increasing proliferation, invasion, and/or metastasis." (PMID 38168907, 2024). "If HGM is detected through Tc-99m pertechnetate scintigraphy in patients with CDH1 mutations, surgical removal of the heterotopic tissue may reduce cancer risk." (PMID 39588436, 2024). "In addition, a cluster of genes associated with epithelial and cancer cells (for example, CDH1, EPCAM, BIRC5 and CD276) was significantly downregulated in resected tumors with nivolumab/relatlimab-induced MPR." (PMID 38689060, 2024). "CDH1 and β-catenin form a complex that regulates downstream target genes like Cyclin D1 and Myc, with its dysregulation linked to poor clinical outcomes in malignant tumors." (PMID 38698370, 2024). "Given the predominantly submucosal growth of cancer foci in CDH1 mutation carriers, additional endoscopic ultrasound (EUS) might offer technological advancement." (PMID 35499650, 2023). "SRCCs are probably included in CDH1-related cancer although the risk seems low." (PMID 37761816, 2023). "One patient with poorly cohesive carcinoma histology harbored a CDH1 mutation." (PMID 37945587, 2023). "When combined with dasatinib in MCF10A-WT and CDH1−/− cells, MK2206 exhibited synergy, indicating that the simultaneous targeting of SRC, DDR2 and AKT may be effective in specifically targeting E-cadherin-deficient cancer cells." (PMID 35406381, 2022). "According to the literature, CDH1 variants could have different clinical manifestations, as they may initiate different cancers." (PMID 35327954, 2022). "CDH1 mutations are associated with metastatic progression in various malignant tumors." (PMID 35402245, 2022).
cancer (continued). "We caution against overinterpreting ethnicity-specific CDH1 associations as only a handful of carriers may drive enrichment in a small cancer cohort." (PMID 34949788, 2022). "Many studies revealed that CDH1 down-regulation may be associated with cancer cells resistant to chemotherapy that can be attributed to the EMT mechanism activation." (PMID 35523936, 2022). "CDH1 gene mutation, DNA hypermethylation silencing, and its encoded E-cad dysfunction are all involved in the invasion and metastatic progression of numerous cancers." (PMID 35784532, 2022). "Germline CDH1 mutations are associated with multiple cancer development." (PMID 35277969, 2022). "Loss of function of CDH1 promotes the progression of cancers and metastasis." (PMID 33869191, 2021). "This research aimed to test whether cancers with CDH1 mutations have heightened sensitivity to histone deacetylase (HDAC) inhibitors." (PMID 35008338, 2021). "In conclusion, entinostat is a promising drug for the chemoprevention and/or treatment of HDGC and may also be beneficial for the treatment of sporadic CDH1-deficient cancers." (PMID 35008338, 2021). "In addition, deregulation of APC/C (a representative E3 ligase) together with its co-activators cell division cycle 20 (CDC20) or CDC20-like protein 1 (CDH1) has been associated with cancers." (PMID 34925455, 2021). "It is possible that the penetrance of cancer risk from pathogenic missense CDH1 variants is lower than that from truncating mutations, and maybe other factors (hormonal)?" (PMID 34066044, 2021). "It warrants clinical study to determine whether Akt inhibitors can effectively treat cancer patients with germline or somatic CDH1 mutations." (PMID 34419139, 2021). "This aim is conducted to postulate whether our findings of unusual secondary cancers in CDH1 mutation patients in Newfoundland and Labrador might warrant careful consideration of other secondary cancer risks in other CDH1 mutation cohorts." (PMID 34073553, 2021). "Finally, we examined the expression of genes that are known to be associated with migration and metastasis of cancer cells, and we observed a significant reduction in E-cadherin (CDH1), an inhibitor of differentiation 1 (ID1) and TWIST2." (PMID 34440702, 2021). "ERBB2 mutation may also be correlated with mutation of E-cadherin (CDH1), a glycoprotein that mediates adhesion between epithelial cells and suppresses cancer invasion." (PMID 31980423, 2020). "Surprisingly, CDH1 mutations contribute to presentation of both cancer and CL/P in 3% of families." (PMID 32260281, 2020). "CDH1 encodes a calcium‐dependent cell adhesion protein [cadherin 1, type 1, E‐cadherin (epithelial)] whose loss can contribute to the metastatic potential of cancer cells." (PMID 32441866, 2020). "Importantly, a cancer-associated single nucleotide polymorphism (SNP, rs16260) facilitates the accessibility of the miRNA-Ago1 complex to the pancRNA_CDH1, increasing CDH1 gene silencing." (PMID 32183847, 2020). "It has been reported that CDH1 may be used in identifying families with high risk of cancer as well as aiding the design of chemopreventive programs that are focused at high-risk subgroups." (PMID 33193601, 2020). "Having identified some cancer cell features (such as CDH1 H-score and ROR score) associated with distant relapse in luminal BC, we next tested variation in TME composition that could be linked to distant relapse in these patients." (PMID 32665033, 2020). "Additionally, expression of E-cadherin (encoded by the CDH1/Cadherin 1 gene) prevents cancer invasion and metastasis." (PMID 32071290, 2020). "Importantly, loss of CDH1 has been shown to be associated with increased invasion or metastasis in several types of carcinoma, and germline mutations have been linked to increased cancer risk." (PMID 32414223, 2020). "Indeed, loss of E-cadherin expression occurring in cancer cells undergoing EMT often correlates with aberrant N-cadherin and cadherin-11 up-regulation." (PMID 31373305, 2019).
cancer (continued). "To identify novel synthetic lethal compounds for the treatment of cancers associated with E-cadherin loss, we have undertaken a high-throughput screening campaign of ~114,000 lead-like compounds on an isogenic pair of human mammary epithelial cell lines – with and without CDH1 expression." (PMID 31467357, 2019). "Taken together, our studies here demonstrate a multilayered interplay between Cdh1 and Src, which might represent as an example of the highly cross-linked, dynamic cancer signaling networks." (PMID 31420536, 2019). "The frequency of CDH1 loss in sporadic and familial DGC, LCIS, and LBC suggests that targeting E-cadherin-deficiency in these cancers may provide an effective method for the chemoprevention of HDGC and new treatments for the sporadic disease." (PMID 31540244, 2019). "The identification of this synthetic lethal relationship may lead to new treatment strategies for hereditary and sporadic cancers with mutations in the CDH1 gene." (PMID 31540244, 2019). "The strong prevalence of these two cancers within the patient’s maternal lineage raised suspicion for possible hereditary diffuse gastric carcinoma (HDGC) secondary to a genetic mutation in the CDH1 gene, particularly based on the recently updated guidelines." (PMID 30007404, 2018). "Identifying CDH1 mutations at the moment of the diagnosis can predict if that cancer is going to be responsive to a therapy and so it could help in choosing the more suitable therapy for a specific patient." (PMID 29094049, 2017). "Given the broad-ranging functions of E-cadherin on tissue organization, it is not surprising that alterations in its expression or structural modifications in its encoding gene CDH1 are common events during cancer progression and contribute to the aberrant morphogenetic effects in cancer." (PMID 29231860, 2017). "The gene involved in the study illustrated a wide range of cancer related cellular events, for example, CDH1 encoded a member of the family of cell adhesion, and abrogation in its expression have been involved in unregulated growth and invasion of adjacent tissues in carcinogenesis." (PMID 28977860, 2017). "Furthermore, the previous studies had very conflicted results with regard to association between CDH1 SNPs and risk of cancers." (PMID 29285016, 2017). "Nevertheless, across sites, the SEER distributions broadly resemble our available Profile stage data in that the proportions of patients displaying evidence of detachment at diagnosis tend to be much greater than our observed CDH1 or CTNNB1 mutation prevalences in primary carcinomas." (PMID 29156750, 2017). "The role of CDH1 or CTNNB1 mutations in generating metastases could potentially vary by carcinoma subtypes within an anatomic site, but such a finer-grained consideration was beyond the scope of the present analysis." (PMID 29156750, 2017). "Though based on a different set of tumors than the Profile data, the SEER data provide an indirect comparison between our observed prevalences of primary carcinomas with a CDH1 or CTNNB1 mutation and proportions of cases diagnosed with some evidence of cancer cell detachment from the primary tumor." (PMID 29156750, 2017). "Of interest, a higher number of H3K4ac marked gene promoters in the MCF10A cell line were associated with genes down-regulated after knock-down of E-cadherin (CDH1) which plays a role in the dynamic epithelial to mesenchymal transition (EMT) response associated with cancer progression." (PMID 26783963, 2016). "We speculate that the recurrent CDH10 mutations we detected in SCLC may perform similar roles as CDH1 mutations in other cancers to promote SCLC aggressiveness, leading to poor patient survival." (PMID 27093186, 2016). "Only 3.4% of ductal/NST carcinomas had inactivating CDH1 mutations." (PMID 27161491, 2016).
cancer (continued). "This analysis revealed that CDH1 may have the prominent roles in the cancer metastasis in terms of their abundant mutational rate across multiple cancer types." (PMID 26486520, 2015). "In respect to this assumption, the reported simultaneous familial occurrence of NSCL/P and cancer could provide clues to consider CDH1 rs1801552 as a potential marker of cancer susceptibility." (PMID 24838934, 2014). "Because hereditary cancers may require different risk reduction, counseling and treatment options than sporadic cancer, it is critical to determine the prevalence of germline CDH1 mutations in patients with ILCA." (PMID 25067988, 2014). "Additionally, a promoting interaction between KLF4 and CDH1 (E-cadherin) has been described, hereby driving cancer cells into an EMT-program through loss of KLF4." (PMID 25593984, 2014). "Further, urothelial tissues affected by UC could be clearly distinguished from normal urothelia based on the presence of aberrant DNA methylation regions in cancer-associated genes such as CDH1, RASSF1A and RUNX3 with sufficient sensitivity and specificity." (PMID 23735005, 2013). "Inactivation of CDH1, encoding E-cadherin, promotes cancer initiation and progression." (PMID 24023670, 2013). "The current hypothesis for how HDGC susceptibility cancers lose their CDH1 heterozygosity and thus their E-Cadherin expression follows the “two-hit” mutation theory." (PMID 21331337, 2011). "The CDH1 gene encodes for a calcium-dependent cell-cell adhesion glycoprotein, whose loss of function may contribute to cancer progression by increasing proliferation, invasion, or metastasis." (PMID 18702824, 2008). "The study found that the active form of vitamin D, 1,25-dihydroxyvitamin D [1,25(OH)2D], could upregulate the expression of the CRC tumor suppressor gene CDH1, and lead to significant changes in the expression of six other genes associated with cancer occurrence." (PMID 40131935, 2025). "Given that CDH1 encodes E-cadherin—a critical cell–cell adhesion molecule for tissue function and integrity—it is not unexpected that its disruption may lead to defects during embryonic development and cancer." (PMID 38414029, 2024). "The E-cadherin protein, produced by the CDH1 gene, may be inactivated in human malignant tumors via various processes, including somatic mutations, genetic abnormalities, activation of transcriptional repressors, abnormal protein processing, and promoter hypermethylation." (PMID 39735013, 2024). "In this work, we demonstrated that regulatory elements lying down-stream of CDH1 are part of a chromatin network that control CDH1 expression and influence cell transcriptome and associated signalling pathways, likely explaining high disease penetrance and very young cancer-onset." (PMID 37249750, 2023). "Loss or dysfunction of CDH1 can lead to compromised barrier function and increased intestinal permeability, which may contribute to various pathological conditions such as inflammation, intestinal injury, and cancer metastasis." (PMID 37662988, 2023). "Furthermore, in vitro analysis of the rs34466743 germline variant from the CDH1 gene confirmed the strength and robustness of the pipeline that could expand the somatic alteration for causing cancer." (PMID 37867380, 2023). "Moreover, in unselected GC patients with CDH1 mutations, cancer risk decreases further." (PMID 35277969, 2022). "Our data suggest that entinostat, in contrast with other potential chemoprevention drugs, may be able to reduce cancer risk by both promoting apoptosis in established CDH1-null foci and preventing the initiation of new foci by maintaining the integrity of the epithelial plane." (PMID 35008338, 2021). "Moreover, reduced expression of CDH1 is linked to the invasion capacity of cancer cells." (PMID 34063128, 2021).